Y_RNA (Y RNA )
Gene: Miscellaneous RNA gene on chromosome X (44,401,603 to 44,401,704, forward strand). Ensembl gene ENSG00000200702.
Homologues: Orthologues: chimpanzee Y_RNA (99% identical), macaque Y_RNA (98% identical), dog Y_RNA (83% identical). Paralogues in human: Y_RNA (91% identical), Y_RNA (89% identical), RNY3 (88% identical), Y_RNA (88% identical), RNY3P1 (87% identical), Y_RNA (87% identical), Y_RNA (86% identical), RNY3P14 (85% identical), Y_RNA (85% identical), RNY3P2 (84% identical), RNY3P7 (84% identical), Y_RNA (84% identical), and 96 more.